AR (androgen receptor)
Diseases named in the same sentence as AR in open-access papers (continued):
Sharing a sentence is not in itself a finding about the gene and the disease.
adenocarcinoma (continued). "Clinical characteristics of NE/SC are quite different from that of CRPC adenocarcinoma, and they are often exemplified by low serum PSA, high serum NE markers (e.g., chromogranin A, neuron-specific enolase), visceral metastasis, and poor response to AR-targeted therapies." (PMID 34884545, 2021). "Moreover, PRNCre allograft tumors manifested a similar breakdown and proportion of the different histological patterns to what was observed in primary tumors of PRN mice (e.g., AR-positive adenocarcinoma and AR-negative, poorly differentiated foci)." (PMID 34099734, 2021). "Irrespective of treatment exposure, adenocarcinoma cells pervasively coexpressed multiple androgen receptor isoforms, including truncated isoforms hypothesized to mediate resistance to androgen-targeting therapies." (PMID 33664492, 2021). "However, as discussed, under potent AR signaling blockade, lineage plasticity and trans-differentiation from AR positive adenocarcinoma to an AR negative small cell/neuroendocrine phenotype occur in a subset of tumors." (PMID 35008216, 2021). "Of note, immunostaining showed that all seven tumors were adenocarcinomas before the treatment, evidenced by staining positive for both AR and PSA, and staining negative for SYP, CD56, and CgA, whereas most of them became AR‐ and PSA‐negative, and SYP‐, CD56‐, and CgA‐positive after ADT." (PMID 33009820, 2021). "Hormonal inhibition of AR signaling is the therapeutic choice for patients with adenocarcinomas, but unfortunately, the disease usually progresses as it becomes independent of exogenous AR induction, leading to castration-resistant prostate cancer (CRPC) with a worse prognosis." (PMID 31694235, 2019). "However, transdifferentiation of the adenocarcinoma to NEPC presents a new challenge to develop an approach to target the AR negative stage of CRPC." (PMID 27542219, 2016). "However, it is likely that the NEPC undergo an AR-independent transition from adenocarcinoma that no longer needs the AR-signaling pathway to survive and grow." (PMID 27542219, 2016). "Despite no apparent association between AR and MET in clinical specimens, evaluation of the xenografts showed that neuroendocrine LuCaP PCa models express higher levels of all cabozantinib targets in comparison to adenocarcinoma models." (PMID 24205338, 2013). "Unlike adenocarcinoma, SCCP lacks PSA secretion and androgen receptor dependence, making preoperative diagnosis exceptionally challenging." (PMID 40746833, 2025). "Next, we examined protein levels of ZBTB10 in a panel of prostate cell lines and found that AR-negative PC3 and NE-like LASCPC01 cells expressed lower ZBTB10 than AR-positive VCaP, LNCaP, C4-2, and 22Rv1 adenocarcinoma cells." (PMID 35306527, 2022). "In the adenocarcinoma ARSI trials, the presence of neuroendocrine markers, even while AR target gene expression was retained, was a strong negative prognostic factor." (PMID 36317634, 2022). "Androgen receptor (AR) and SV40 T antigen were detected immunohistochemically in a diffuse pattern in areas of PIN and adenocarcinomas in the ventral prostate, with differences not observed among the groups." (PMID 27973395, 2016). "Unlike PCA, which is usually adenocarcinoma, NEPC tumors lose their dependence on AR signaling, and the regulation of many metabolic processes by AR is correspondingly reduced, the activation of related signaling pathways and chromatin modifications lead to metabolic reprogramming." (PMID 37061523, 2023). "Notably, unlike typical adenocarcinomas, such SmCCs do not consistently express ERG immunohistochemically, likely because of the lower frequency of expression of the androgen receptor (AR) by these cells." (PMID 29581876, 2018).
infection (60 papers, 2010 to 2025). The state of being infected such as from the introduction of a foreign agent such as serum, vaccine, antigenic substance or organism. "The basis of male susceptibility might be explained by the results obtained in murine models, where males are more susceptible to the infection due to the viral recognition of the androgen receptor present in male mice." (PMID 36142219, 2022). "Notably, this is closely linked to the infection-related failure of homeostatic HPG axis feedback to compensate for weakened AR signalling." (PMID 36303865, 2022). "It has also been postulated that susceptibility to infection may vary based on ethnic variation in allele distribution of the androgen receptor." (PMID 33728145, 2021). "Interestingly, ASOs targeting the androgen receptor (AR) also decreased B.1.1.7 variant infectivity in iAEC2 cells, suggesting infection of iAEC2 might be AR-regulated." (PMID 36735698, 2023). "The abundance of AR genes in X. oryzae’s genome has a major impact on its ability to adapt and establish infection in its host plant." (PMID 39768396, 2024). "Enzalutamide reduced TMPRSS2 expression by inhibiting AR activity in LNCaP and VCaP cells, and significantly inhibited infection of these prostate cells by both authentic SARS-CoV-2 or SARS-CoV-2-S pseudovirus." (PMID 33558541, 2021). "We also find the presence of host factors, ACE2, TMPRSS2, and AR, to overlap with the infection sites." (PMID 35602214, 2021). "The antigenic CTL epitope showed the strong binding with HLA-A*0201 receptor protein and with androgen receptor (specific receptor for MAGE-A11 during infection) with high molecular docking scores." (PMID 33169789, 2020). "Gonadectomy increased AR mRNA expression by PBMCs from naïve male mice, whereas testosterone treatment reduced AR mRNA expression during infection (compared to that in gonadectomized mice)." (PMID 32651360, 2020). "Conversely, when disease following infection is largely attributable to immunopathology, the immunomodulatory effects of testosterone, and more specifically, AR signaling, are likely protective." (PMID 32645119, 2020). "Since maintenance of EAV long-term persistent infection is testosterone-dependent, immunohistochemical (IHC) evaluation of the androgen receptor (AR) was undertaken to assess the cellular expression within the ampulla." (PMID 31356622, 2019). "(A) The LNCaP and CWR22Pc-EP reporter cell lines were generated by lentiviral infection with the eGFP AR reporter construct (details can be found in Materials and methods)." (PMID 30644358, 2019). "Strong AR against Mo isolate Guy11 was established in the region adjacent to P. syringae DC3000 infection area in the wild-type plants." (PMID 30386355, 2018). "We next infected mice by the I.N. route with a lethal dose of LVS (3 × 103 CFUs/mouse) and then treated the infected mice, starting about 1 h post-infection, once daily by I.P. injection with 2.5, 5, or 10 mg AR-13/kg/day in 200 μl PEG for 10 days." (PMID 28955308, 2017). "Weconfirmed that AR can co-immunoprecipitates with activated EphA2 during KSHV primary infection, along with Src." (PMID 28957431, 2017). "Are the reproductive tissues more likely to be affected by infection, and does a yet to be identified infectious agent confer upon the androgen receptor its features, reminiscent of acquired resistance?" (PMID 25265995, 2014). "Progestins found in higher dosages in DMPA can block the androgen receptor and prevent infection of T. vaginalis." (PMID 26316977, 2014). "We found that the primary gene networks elevated in males compared to females at 12 h after infection involved cholesterol metabolism and activation of the androgen receptor (AR) in immune cells." (PMID 21338512, 2011). "We found that, compared to females, male mice had a greater splenic expression of genes which are important for cholesterol metabolism and activation of the AR at 12 h after infection." (PMID 21338512, 2011).
infection (continued). "In addition to DEX activating GR, KLF15 can cooperate with the progesterone receptor and/or the androgen receptor to activate bovine herpesvirus (BoHV-1) immediate early gene expression, which enhances productive infection." (PMID 40872334, 2025). "Infection of multiple HDF strains with an ANKRD1-expressing lentivirus resulted in increased ANKRD1 protein levels comparable to those found in CAFs or HDFs with AR gene silencing." (PMID 38310103, 2024). "Our previous work showed that infection by SARS-CoV-2 could be attenuated by treatment with AR or BET inhibitors, which decreased expression of the critical host entry factors ACE2 and TMPRSS2." (PMID 36735698, 2023). "Limited AR typing as conducted in this study is affordable and, in conjunction with data such as dates and times of contamination/infection, can be valuable in identifying presumptive cross contamination and so prompt a review of infection control procedures to address likely deficiencies." (PMID 36782258, 2023). "In addition, a moderate activity was detected in cell pre-treatment, when peptides were incubated on cells prior the infection, suggesting a putative action of RV-23 and AR-23 on the cell surface that interferes with the virus–cell binding." (PMID 37894104, 2023). "One hypothesis to account for this infection gender discrepancy is that viral entry is potentially enhanced in the lungs and other tissues of men through AR-mediated upregulation on TMPRSS221." (PMID 34341347, 2021). "We find ACE2, TMPRSS2 and AR expression to overlap with the infection sites." (PMID 35602214, 2021). "As the common function of LRs in promoting KSHV primary infection, we speculated that co-localized AR may play a concordant role in KSHV infection of target cells." (PMID 28957431, 2017). "In addition, infection of LNCaP cells with lentiviral vectors harbouring these AR-Vs resulted in androgen-independent proliferation at lower virus titres, but suppression of proliferation at higher virus titres." (PMID 27897170, 2016). "With similar infection efficiency, exogenous addition of AR via a lentiviral vector in BFTC cells (GFP-positive cells) increased the viability of cells under various concentrations of doxorubicin treatment compared with cells transfected with pWPI control vector." (PMID 23599788, 2013). "Representative images of cellular infectivity by the WA1 strain of SARS-CoV-2 in control-, proxalutamide-, or enzalutamide-treated conditions confirmed that decreased infection could be achieved by the AR antagonists proxalutamide and enzalutamide in LNCaP cells." (PMID 37459541, 2023). "Therefore, we compared AR mRNA expression in PBMCs from sham-operated and gonadectomized naïve male mice, and from gonadectomized and testosterone-substituted male mice, upon infection." (PMID 32651360, 2020). "Activation of the androgen receptor (AR) stimulates the production of TMPRSS-2, a viral spike protein-S1 stimulator, an essential protein for host cell infection, through interaction with ACE-2." (PMID 37627478, 2023). "In conjunction with the androgen receptor, androgens activate TMPRSS2 expression, which plays a vital role in internalizing the SARS-CO-V2 virus and productive infection." (PMID 33915795, 2021). "In the present study, we have confirmed the role of both AR and its ligand in promoting KSHV primary infection in target cells." (PMID 28957431, 2017). "AR was silenced in MGC803 and SGC7901 cells which showed relative high basal levels of AR expression by lentivirus infection." (PMID 28388558, 2017). "Accordingly, compared with the control groups, at 48 h post-infection (p.i.), we observed a dramatic inhibition of nuclear LANA immunostaining in AR and EphA2 siRNA-treated SLK cells." (PMID 28957431, 2017).
infection (continued). "Age > 60, a clinical factor associated with the TLT subtype, was associated with 57 upregulated genes, including BCR signaling genes, IL6 (related to infection), and IL21R (different from TLT vs. ME), and 141 downregulated genes including EPCAM, AR, WT1, and CD28." (PMID 39866884, 2025). "Thus, Calu-3 cells, which express AR and TMPRSS-2 and thereby mimic natural infection, were used for further experiments." (PMID 36834705, 2023). "Besides coronaviruses family, TMPRSS2 function in a similar way to the de novo infection of IAV, which is also regulated by androgen/AR axis." (PMID 34803967, 2021). "There was no obvious cell toxicity after infection with androgen receptor-expressing retroviruses, and we did not detect any morphological changes in infected cells." (PMID 32269992, 2020). "To assess whether the testosterone-induced changes in CD8+ T cell numbers and activity were also AR-dependent, we evaluated the effects of flutamide on the contraction of CD8+ T cells during the resolution phase of infection." (PMID 32645119, 2020). "Acute phase response signaling, which provides a rapid non-specific inflammatory response against infection, was also dominated by 17 AR-DE genes up-regulated in the Rf + embryo, compared to only 5 genes that were expressed higher in liver of the Rf- embryos." (PMID 29506485, 2018). "Viral burden in STAT1−/−/AR−/− mice was equivalent to STAT1−/−/2−/− mice in all tissues at 72 hours post-infection (data not shown)." (PMID 21379341, 2011). "Interestingly, the infection of T. crassiseps did not induce significant changes in the expression of ERα, Erβ, or AR in the infected male and female mice compared with their control group." (PMID 35335632, 2022). "NRF-2 and AR belong to CNC-bZIP and steroid nuclear receptor (NR) families of TFs, respectively, whose binding motifs were significantly enriched in the accessible ATAC-seq peaks from JQ-1-treated cells independent of infection." (PMID 37747932, 2023). "Following intravenous infection with 1010 GE of S221, 100% of STAT1−/−/AR−/− mice developed early lethal disease, whereas none of the STAT1−/−/GR−/− mice succumbed to infection, demonstrating that the survival phenotype of STAT1−/−/AR−/− mice recapitulates that of STAT1−/−/2−/− mice." (PMID 21379341, 2011).
neurodegenerative disease (30 papers, 2011 to 2025). A disorder of the central nervous system characterized by gradual and progressive loss of neural tissue and neurologic function. "By contrast, accumulation of abnormal AR is a pathogenic signature of spinal and bulbar muscular atrophy, a poly-glutamine-induced neurodegenerative disease and AR splice variants have been detected in the nervous system." (PMID 36766714, 2023). "Spinal and bulbar muscular atrophy (SBMA) is an adult-onset hereditary neurodegenerative disease caused by the expansions of CAG repeats in the androgen receptor (AR) gene." (PMID 35821212, 2022). "The role of androgen/AR axis in neuritogenesis and neurodegenerative diseases is still debated, with most studies performed in neuronal cells." (PMID 36766714, 2023). "Our results highlight a similar pattern of dysregulation for two key AR co-activators in an androgen-dependent neurodegenerative disease." (PMID 36746939, 2023). "Effect of polyQ1 length of AR on PCa and neurodegenerative disease like SBMA has been confirmed but there is a need for validation on the effect of polyG and polyP and their interplay before targeting." (PMID 36388907, 2022). "DCTN1 is reduced in mice with spinal and bulbar muscular atrophy (SBMA), a hereditary neurodegenerative disease and over-expression of DCTN1 mitigated neuronal toxicity of the pathogenic androgen receptor in a cell culture model of SBMA30." (PMID 29915338, 2018). "SBMA is a late-onset neurodegenerative disease, caused by an extreme expansion of trinucleotide CAG repeats in the AR gene first exon, which encodes for a stretch of glutamines (polyQ) in the N-terminal transactivation domain of the AR protein." (PMID 26157390, 2015). "Accumulation of AR in the nucleus may also derive from malfunctions of the nucleocytoplasmic transport machinery, which is indeed defective in several neurodegenerative diseases." (PMID 32019272, 2020). "Altered protein homeostasis underlies degenerative diseases triggered by misfolded proteins, including spinal and bulbar muscular atrophy (SBMA), a neuromuscular disorder caused by a CAG/glutamine expansion in the androgen receptor." (PMID 22022281, 2011). "A further dissection of the effect of these direct and indirect pathways on suppressing mutant ataxin-1 and AR toxicity could provide critical insights into the role of Nlk in neurodegenerative diseases and whether there is a unifying protective effect of Nlk reduction." (PMID 37384409, 2023). "Numerous evidence also indicated that PARP1, SCD, AR, ALOX5, HIF1A are critical involved in HD or neurodegenerative diseases." (PMID 38918688, 2024). "Given the surprisingly high frequency of the AR repeat expansion, we sought to carry out our analysis on replication datasets, using North American (NIH and gnomAD) and European (Project MinE) cohorts, where control and neurodegenerative diseases were sequenced with WGS10,19." (PMID 36797998, 2023).